PARP1 (poly(ADP-ribose) polymerase 1)
Diseases named in the same sentence as PARP1 in open-access papers (continued):
Sharing a sentence is not in itself a finding about the gene and the disease.
Arthritis (9 papers, 2006 to 2025). Inflammation of a joint. "Nevertheless, both genetic deficiency and chemical inhibition of PARP-1 attenuates experimental arthritis in the mouse." (PMID 27626929, 2016). "Our group investigated the impact of the selective suppression of PARP-1, using PARP-1 deficient mice, in a model of arthritis induced by anti-collagen antibodies (CAIA)." (PMID 26339143, 2015). "To investigate the contribution of PARP-1 to experimental arthritis, we induced CAIA in control and PARP-1 deficient mice." (PMID 16356201, 2006). "PARP-1 deficient mice had decreased severity in clinical and histological arthritis, although the incidence of disease was similar in control and deficient mice." (PMID 16356201, 2006). "We show that PARP-1 deficiency partially reduces the severity of arthritis, although the incidence of disease was similar in control and deficient mice." (PMID 16356201, 2006). "It remains possible that the decreased severity of arthritis observed in PARP-1 deficient mice was associated with reduced neutrophil exudate in joints from these mice." (PMID 16356201, 2006). "PARP-1 deficient mice consistently displayed significantly lower severity of arthritis than parp-1+control mice (p = 0.03 by repeated measures 1-way ANCOVA test) all through the follow-up." (PMID 16356201, 2006). "The studies of the role of PARP-1 in experimental arthritis models started in the 1990s, using unspecific inhibitors such as nicotinamide (NA) and nicotinic acid amide (NAA)." (PMID 26339143, 2015). "Overall, our results indicate that PARP-1 plays a role in arthritis progression, probably through impaired IL-1β and MCP-1 production in joints." (PMID 16356201, 2006). "In eight separate experiments, male and female parp-1+/+ (n = 18), parp-1+/o (n = 8) and parp-1o/o (n = 19) mice were injected with Arthrogen and lipopolysaccharide and monitored for signs of arthritis." (PMID 16356201, 2006). "Here we report the impact of selective PARP-1 suppression on the collagen antibody-induced arthritis model (CAIA)." (PMID 16356201, 2006). "The aim of this study was to analyze the impact of selective PARP-1 suppression in collagen antibody-induced arthritis." (PMID 16356201, 2006). "Several studies using experimental arthritis models or pharmacological and genetic inhibition of PARP-1 in FLS from RA patients have revealed the involvement of this protein in the pathogenesis of arthritis and the potential therapeutic effects of PARP-1 inhibition." (PMID 26339143, 2015). "Here, we investigate the impact of a selective PARP-1 inhibitor in experimental arthritis." (PMID 17971849, 2007). "Given the involvement of PARP-1 in inflammation, we considered that it could have a role in the effector phase of arthritis; the CAIA model specifically reflects this phase." (PMID 16356201, 2006). "PARP-1 inhibition with 5-aminoisoquinolinone (AIQ) significantly reduces incidence and severity of established collagen-induced arthritis, completely abrogating joint swelling and destruction of cartilage and bone." (PMID 17971849, 2007). "We have found that the absence of PARP-1 partially reduced the severity of arthritis, likely by the impairment of IL-1β and monocyte chemotactic protein (MCP)-1 transcription in arthritic tissue." (PMID 16356201, 2006). "Indeed, PARP1 and HOXA1 have been reported as key molecules in IL‐1β‐related inflammatory osteolysis and chondrocyte degradation, respectively, in human diseases such as arthritis." (PMID 40545975, 2025). "Interestingly, the PARP-1 inhibitors PJ34 and AIQ also showed a prophylactic effect, as a protective effect was observed when the inhibitors were administered after the onset of arthritis." (PMID 26339143, 2015). "Moreover, PARP-1 inhibition reduced the expression of several proinflammatory chemokines receptors involved in arthritis pathology (not shown), reflecting also a decreased joint inflammatory infiltration." (PMID 17971849, 2007).
Arthritis (continued). "Thus, lack of PARP-1 does not impair neutrophil exudation in this arthritis model." (PMID 16356201, 2006).
cerebellar ataxia (9 papers, 2019 to 2025). A neurological syndrome characterized by clumsy and uncoordinated movement of the limbs, trunk, and cranial muscles. "Intriguingly, we also detected increased PARP1 trapping in primary human fibroblasts from XRCC1-mutated disease, and we reported recently that loss of cerebellar interneurons and cerebellar ataxia in Xrcc1-deleted mice are suppressed greatly by Parp1 deletion." (PMID 34102106, 2021). "Recently, we demonstrated using an Xrcc1‐defective mouse model (Xrcc1Nes‐Cre) that SSBR‐defective cerebellum possesses elevated steady‐state levels of poly(ADP‐ribose) resulting from the hyperactivation of Parp1, leading to the loss of cerebellar interneurons and cerebellar ataxia." (PMID 33932076, 2021). "To understand the basis for ataxia present in the AtmNes-cre;Aptx−/− and the AtmNes-cre;Parp1−/− mice, we evaluated nervous system histology." (PMID 34910524, 2021). "We reported previously that Parp1 is hyperactive in the cerebellum of Xrcc1Nes‐Cre mice, resulting in cerebellar ataxia." (PMID 33932076, 2021). "Indeed, we have shown previously that Parp1 hyperactivation accounts for the cerebellar dysfunction and ataxia that is observed in Xrcc1Nes‐Cre mice." (PMID 33932076, 2021). "Interestingly, the genetic inactivation of Parp1 (poly (ADP) ribose polymerase 1) rescued ADP ribose levels and reduced the loss of cerebellar neurons and ataxia in Xrcc1-defective mice, implying that PARP1 hyperactivation was neurotoxic to cerebellar neurons." (PMID 32630049, 2020). "Thus, preventing the binding of PARP1 to DNA but not its enzymatic inhibition can be exploited for the therapeutic treatment of clinical cerebellar ataxias associated with unrepaired SSBs." (PMID 30991935, 2019). "An occasional Aptx−/−;Parp1−/− animal developed a late-onset gait phenotype characterized by dystonia and hind limb dysfunction, but they lacked overt ataxia." (PMID 34910524, 2021). "Last, to distinguish the contribution of ATM inactivation to this phenotype, we also established Aptx−/−;Parp1−/− mutant animals, but these did not develop ataxia." (PMID 34910524, 2021). "The hyper-recombination as well as the cerebellar ataxia phenotype in Xrcc1 knockout mice is rescued by Parp1 gene deletion but not by enzymatic inhibition of PARP1." (PMID 30991935, 2019).
endometrial cancer (9 papers, 2008 to 2024). Primary or metastatic malignant neoplasm involving the endometrium (mucous membrane that lines the endometrial cavity). "The highfrequency of uterine neoplasm in PARP-1−/− female mice is reminiscent of a previous report correlating the loss of PARP-1 and development of endometrial carcinomas in humans." (PMID 19415146, 2008). "In addition, our data also strongly suggest that inhibiting DHODH alone and in combination with the PARP1 inhibitor promotes replication-associated genomic instability and significantly decreases the survival of endometrial cancer cells." (PMID 38136273, 2023). "Further, we analyzed the enriched RNAs in apoptosis pathways, and the CPTAC database showed that their encoded proteins were upregulated in endometrial cancer tissues, including ITPR3, LMNB1, PARP1, PARP4, and TUBA1C." (PMID 36566215, 2022). "Here, we tested whether treatment with a PARP1 inhibitor (Olaparib) in combination with a DHODH inhibitor (teriflunomide) synergized to increase DSBs in endometrial cancer cells." (PMID 38136273, 2023). "Although PARP1 promoter methylation is involved in the regulation of PARP1 expression in human keratinocyte lines and lymphoblastoid cell lines, its roles in human endometrial cancer are unknown." (PMID 23762867, 2013). "Then we analyzed the RNAs enriched in the apoptotic pathway through CPTAC database, and showed that the protein level of ITPR3, LMNB1, PARP1, PARP4, and TUBA1C were upregulated in endometrial cancer tissues." (PMID 36566215, 2022). "Furthermore, the stability of PARP-1 mRNA in endometrial cancer cells is significantly modulated by the expression of SNORD104, which is able to induce 2′-O-methylation in specific residues of PARP-1 mRNA thanks to its interaction with FBL." (PMID 38406265, 2024). "Our findings imply that PARP1 overexpression may participate in endometrial cancer progression, and abnormal hypomethylation of CpG sites within the ETS motif in the core promoter region may be responsible for PARP1 overexpression in EAC tissues." (PMID 23762867, 2013). "Additionally, expression of ICAD as well as PARP-1 was reported to be altered in endometrial carcinomas compared with non-neoplastic endometrial tissues, indicating impaired mechanisms of apoptosis in the former." (PMID 23451280, 2013).
epilepsy (9 papers, 2017 to 2025). A brain disorder characterized by episodes of abnormally increased neuronal discharge resulting in transient episodes of sensory or motor neurological dysfunction, or psychic dysfunction. "We found that RP11-267M23.4, NBL1, ENTPD3-AS, RNF157, ZNF619, RPL14, and PARP1 showed causal relationship to epilepsy." (PMID 40624693, 2025). "In epilepsy, mapping our m6A-associated genes (e.g., PARP1, NBL1, RPL14) to their proteomic counterparts identified causal links to proteins such as ST6GALNAC5, CTNNA2, and TOM1L1, highlighting specific m6A-driven regulatory cascades at the protein level." (PMID 40624693, 2025). "KIF4 mutations increased the affinity of binding with PARP1 and contributed to epilepsy susceptibility." (PMID 38801174, 2024). "Among all exposure genes, RP11-267M23.4, ENTPD3-AS, ZNF619, and RPL14 were demonstrated as risk factor to epilepsy, while NBL1, RNF157, and PARP1 were protective factors to epilepsy." (PMID 40624693, 2025). "While LSR’s role in neuroinflammation, PARP1’s involvement in neuronal survival, and ZNF619’s regulation of transcription are consistent with epilepsy pathophysiology, these associations are based on a limited sample size and bulk‐tissue expression." (PMID 40624693, 2025). "In PTZ-induced epileptic models, the knock-out of TRPM2 has shown efficacy in ameliorating epilepsy-induced hippocampal pathological damages, probably via the PARP1 downstream signaling pathway involving BNIP3." (PMID 40217519, 2024). "As a matter of fact, inhibition of PARP‐1 has been recognized as a beneficial strategy for epilepsy." (PMID 38801174, 2024). "PARP1, a gene involved in DNA repair and stress responses, could influence neuronal survival and excitability in epilepsy." (PMID 40624693, 2025). "Therefore, while PARP1 plays a neuroprotective role under normal conditions, its reduced activity due to KIF4 mutation becomes a risk factor for epilepsy, highlighting PARP1 as a potential therapeutic target for antiepileptic interventions." (PMID 40624693, 2025). "The neuroprotective effect of TRPM2 knockout could decrease neuronal apoptosis via PARP‐1/BNIP3/AIF in epilepsy." (PMID 38801174, 2024). "In the MR analysis with epilepsy as the outcome, we identified seven positive results: RP11-267M23.4, NBL1, ENTPD3-AS1, RNF157, ZNF619, RPL14, and PARP1." (PMID 40624693, 2025).
esophageal cancer (9 papers, 2015 to 2025). A primary or metastatic malignant neoplasm involving the esophagus. "For the first time, YM155-induced PARP-1-dependent parthanatos cell death has been observed in esophageal cancer cells, and the underlying cytotoxic mechanism is tightly linked to PARP-1 hyper-activation leading to PAR formation and AIF translocation." (PMID 26090615, 2015). "Examining the association of PARP1 expression with different genotype of rs8679 in esophageal cancer tissues may be helpful in providing mechanistic evidence for the results." (PMID 33112558, 2020). "YM155 killed esophageal cancer cells by causing DNA damage and the hyper-activation of PARP-1 and the translocation of AIF, leading to PARP-1-dependent cell death." (PMID 26090615, 2015). "Based on transcription of upregulated genes, we further confirmed the excessive activation of PARP-1 upon YM155 treatment in esophageal cancer cells." (PMID 26090615, 2015). "Having shown that YM155 treatment induces PARP-1-dependent parthanatos cell death in esophageal cancer cells in vitro, we next investigated the efficacy of YM155 in inhibiting KYSE410 and KYSE150 tumor growth in a mouse xenograft model of esophageal cancer." (PMID 26090615, 2015). "The statistically higher expressions of PLAUR, BIK, DRAM2, RNF41, STK38, ATG5, and PARP1 were measured in esophageal cancer than those in normal tissue, while statistically significant differences were also detected between ESCC and esophageal adenocarcinoma (EAC)." (PMID 32974198, 2020). "Similarly, Moringa oleifera extract, rich in polyphenols, induced DNA damage and inactivated PARP1 in human esophageal cancer cells." (PMID 30171426, 2018). "Thus, YM155 is a novel inducer of PARP-1-dependent parthanatos cell death and has potential as an effective esophageal cancer treatment." (PMID 26090615, 2015). "In conclusion, we report that YM155 treatment can kill esophageal cancer cells by causing DNA damage, PARP-1 hyper-activity, and AIF translocation leading to PARP-1-dependent parthanatos cell death and that it reduced tumor burden in both in vitro and in animal models in vivo of esophageal cancer." (PMID 26090615, 2015). "Oncogenic miR-223 has been found to diminish DNA repair and apoptosis potentials of esophageal cancer cells and increase the resistance to DDP via targeting and down-regulating Poly (ADP-ribose) polymerase 1 (PARP1)." (PMID 34881242, 2021). "Although research on PARP-1’s role in BE development and GERD-related esophageal cancer is limited, preliminary findings suggest that PARP-1 overexpression may confer resistance to oxidative stress and bile acid-induced damage in BE epithelial cells." (PMID 40149421, 2025). "As PARP2 and PARP1 play similar roles in DDR, this may suggest an oncogenic role for both enzymes in oesophageal cancers." (PMID 34440228, 2021). "Fourthly, we did not measure the expression level of PARP1 in esophageal cancer tissues with different genotype of rs1136410 and rs8679 SNPs." (PMID 33112558, 2020).
Fanconi anemia (9 papers, 2014 to 2024). Fanconi anemia (FA) is a hereditary DNA repair disorder characterized by progressive pancytopenia with bone marrow failure, variable congenital malformations and predisposition to develop hematological or solid tumors. "This SUMO–RNF4 axis has been shown to generate the ubiquitinated products required for p97 extraction of Fanconi anemia ID complex components in response to DNA damage and to remove cytotoxic trapped PARP1 from chromatin." (PMID 36880596, 2023). "Recent studies have shown that the disruption of any HR-related pathway, such as by BRCA mutations, and disruption of Fanconi anemia, and ATM genes, can predict the sensitivity of tumors to the inhibition of PARP1 by small-molecule inhibitors and the associated cytotoxicity." (PMID 28820388, 2017). "Previous studies showed that non-homologous end joining (NHEJ), homologous recombination (HR) via the Fanconi anaemia (FA) pathway, and poly(ADP-ribose) polymerase 1 (PARP1)–dependent DNA repair are involved in the repair of AzadC-induced DNA lesions." (PMID 38906675, 2024). "Our idea to analyze EVI1 as a relevant protein in Fanconi anemia and thus in DNA repair mechanisms would hint at an interaction of EVI1 and PARP1 in this regard." (PMID 37525239, 2023). "Some of these results have implications outside hematopathology: in individuals other than those with Fanconi anemia, biomarkers of the FA/BRCA pathway can be used to predict the cisplatin or PARP1 (poly ADP ribose polymerase 1) inhibitor sensitivity of certain cancers." (PMID 38023340, 2023). "Indeed, proteasome inhibitors block Fanconi anemia and homologous recombination pathways, rendering MM cells addict on BER initiated by PARP1/2-mediated Poly(ADP-ribosyl)ation of proteins." (PMID 24809299, 2014).
Hypoglycemia (9 papers, 2012 to 2024). A decreased concentration of glucose in the blood. "It has been suggested that cognitive dysfunction after hypoglycemia is related to selective neuronal death, and its underlying mechanism involves excitotoxicity, oxidative stress, zinc release, PARP-1 activation, blood–brain barrier dysfunction and mitochondrial dysfunction." (PMID 39193149, 2024). "Hypoglycemia may lead to neuronal death by promoting oxidative stress, zinc release, poly(ADP-ribose) polymerase 1 activation, and mitochondrial dysfunction, and the neuronal damage and cognitive decline caused by severe hypoglycemia are exacerbated by diabetes." (PMID 39123214, 2024). "Recurrent moderate hypoglycemia (R/M hypoglycemia)-induced PARP-1 activation depends on cytoplasmic NAD." (PMID 36769273, 2023). "NAD is an essential component of glycolysis, and even when glucose availability is restored by PARP-1 activation after hypoglycemia, cells become unable to use glucose, resulting in ATP depletion." (PMID 36769273, 2023). "Taken in this context, the present findings suggest that pyruvate promotes neuronal survival after hypoglycemia by bypassing a sustained impairment in glycolysis induced by PARP-1 activation." (PMID 24278448, 2013). "Furthermore, administration of a zinc chelator in brain can block hypoglycemia-induced PARP-1 activation and neuronal death." (PMID 24278448, 2013). "Activated PARP-1 consumes cytosolic NAD, and because NAD is required for glycolysis, hypoglycemia-induced PARP-1 activation may render cells unable to use glucose even when glucose availability is restored." (PMID 24278448, 2013).
renal cell carcinoma (9 papers, 2017 to 2024). "Consistently, DOC-2/DAB2 interactive protein (DAB2IP) can form a complex with PARP-1 and its identified E3 ligase in renal cell carcinoma (e.g., RanBP2, TRIP12, RNF40, and VHL), leading to PARP-1 degradation." (PMID 36694209, 2023). "DAB2IP can interact with PARP-1 and contribute to E3 ligase–mediated ubiquitylation and degradation of PARP-1, which increases the radiosensitivity of renal cell carcinoma cells." (PMID 34775484, 2022). "Several clinical trials are ongoing to study the effect of PARP-1 inhibitors on participants with renal cell carcinomas." (PMID 34638458, 2021). "Additionally, in NONO-TFE3 translocation renal cell carcinoma (NONO-TFE3 tRCC), a subtype of RCC associated with Xp11.2 translocation/TFE3 gene fusions RCC (Xp11.2 tRCCs), YTHDF2 played a tumor-suppressive role by suppressing poly(ADP-ribose) polymerase 1 (PARP1) expression." (PMID 38503745, 2024).